ABCB1 (ATP binding cassette subfamily B member 1)
Diseases named in the same sentence as ABCB1 in open-access papers (continued):
Sharing a sentence is not in itself a finding about the gene and the disease.
cancer (continued). "The MDR reversal ability of caffeic acid was examined in both P-gp over-expressing cell line ABCB1/Flp-InTM-293 and MDR cancer cell line KB/VIN." (PMID 31936160, 2020). "Nevertheless, the effect of regular treatment with erdafitinib on ABCB1 and ABCG2 in cancer patients remains to be further investigated." (PMID 32466597, 2020). "Two efflux transporters from the ATP-binding cassette (ABC) family, ABCB1 and ABCG2, are thought to contribute to multidrug resistance (MDR) in cancer." (PMID 31729540, 2020). "Nevertheless, the effect of long-term regular treatment of sitravatinib on ABCB1 and ABCG2 in human cancer cells remains to be determined." (PMID 31941029, 2020). "As an alternative, we and others have been investigating the potential repurposing of tyrosine kinase inhibitors (TKIs) as modulators of ABCB1 and ABCG2 to resensitize multidrug-resistant cancer cells to chemotherapeutic agents." (PMID 31941029, 2020). "The ABC transporter subfamily B member 1 (ABCB1/MDR1, P-glycoprotein, Pgp) is one of the most important transporters to confer MDR to cancer cells." (PMID 32133044, 2020). "In this study, we investigated the efficacy of methyl-cantharidimide (MCA), a cantharidin (CTD) analog, as an anticancer drug, in cancer cells overexpressing either ABCB1 or ABCG2 transporters and in cisplatin-resistant cancer cells." (PMID 32676451, 2020). "Several receptor tyrosine kinase inhibitors (RTKIs) have been reported to interact strongly with ABCB1 and/or ABCG2 and reverse multidrug resistance in cancer cells overexpressing ABCB1 and/or ABCG2." (PMID 32466597, 2020). "Considering that the reversal of MDR in cancers sometimes can be due to lowered expression of the protein, we further investigated the effect of ERK5-IN-1 on the expression of ABCB1 at protein and mRNA levels." (PMID 32164732, 2020). "Both doxorubicin-resistant LoVo/Dx and HT29/Dx cell lines are characterized by overexpression of ABCB1 protein (MDR1, P-glycoprotein), the main multispecific transporter involved in multidrug resistance (MDR) of cancer cells." (PMID 33065997, 2020). "We discovered that at submicromolar concentrations, sitravatinib re-sensitizes ABCB1- and ABCG2-overexpressing multidrug-resistant cancer cells to chemotherapeutic drugs." (PMID 31941029, 2020). "ABCB1 and ABCG2 expression correlate with resistance to cisplatin and paclitaxel in cancer cells and in cells from patients and mice." (PMID 32157214, 2020). "The cancer MDR reversing ability of caffeic acid was then evaluated in both ABCB1/Flp-InTM-293 and KB/VIN MDR cancer cell lines." (PMID 31936160, 2020). "We conducted experiments to determine the anti-cancer efficacy of EC16-1/saporin and its interaction with the ABC transporters ABCB1 and ABCG2." (PMID 32098067, 2020). "We demonstrated that by modulating the transport function of both ABCB1 and ABCG2, sitravatinib re-sensitizes ABCB1- and ABCG2-overexpressing multidrug-resistant cancer cells to chemotherapeutic agents." (PMID 31941029, 2020). "Our results indicated that our parental ABCB1- and ABCG2-overexpressing cells were an acceptable model to evaluate the anti-cancer and reversal efficacy of EC16-1/saporin." (PMID 32098067, 2020). "Expression of the major ABC transporters, including ABCA1, ABCB1, ABCC1, ABCC2, ABCC3 and ABCG2, was assessed in chemoresistant cancer cells transfected with si-ERRγ." (PMID 32206097, 2020). "Among these members, P-glycoprotein (P-gp, also referred to as multidrug resistance protein 1, MDR1, or ABCB1) is the best characterized efflux pump that mediates cancer MDR." (PMID 33096917, 2020). "Although expression of both ABCB1 and ABCG2 are commonly considered only in epithelial cells or cancer cells, the predominant expression of these pumps in prostate is in endothelial cells." (PMID 32584883, 2020).
cancer (continued). "Regarding the drug transporter regulation, it is known that efflux transporters ABCG2 (BCRP) and ABCB1 (P-gp) are induced by TCDD mediated AhR activation in Caco-2 and other human carcinoma cells including HepG2, LS180, LS174T and MCF7 cells." (PMID 33551819, 2020). "For instance, studies have revealed that FK228 (romidepsin) is a substrate of both ABCB1 and ABCG2, and that continuous exposure to FK228 induces expression of ABCB1 and ABCG2 in cancer cells." (PMID 31905792, 2019). "The IC50 of doxorubicin, paclitaxel, and vincristine decreased with the combination of ZA-A, ZA-B and ZA-C in both P-gp over-expressing cell line (ABCB1/Flp-InTM-293) and MDR cancer cell line (KB/VIN)." (PMID 31766413, 2019). "Some of these resistance mechanisms, specifically the over-expression of ABCB1 and CD44 molecules among others, develop because of WNT signaling pathway deregulation in the cancer stem cell subset." (PMID 31921125, 2019). "First, the cytotoxicity of glesatinib to P-gp overexpressing cancer cells KB-C2, SW620/Ad300, HEK293/ABCB1, and their parent cells KB-3-1, SW620, HEK293 cells were determined by MTT assay." (PMID 31106148, 2019). "Recent studies have proposed another potential mechanism by which cancer cells acquire MDR, which is intercellular transfer of ABCB1." (PMID 31830995, 2019). "In another study, the downregulation of CD44 protein by siRNA in cancer cells from patients with ovarian carcinoma confirmed that the mRNA levels of CD44 and ABCB1 correlate positively." (PMID 31921125, 2019). "In the present study, we report an additional function of TMP195 in reversing ABCB1- and ABCG2-mediated multidrug resistance in cancer cells." (PMID 31905792, 2019). "Next, we examined the effect of TMP195 on apoptosis induced by ABCB1 substrate drug colchicine and by ABCG2 substrate drug topotecan, known inducers of apoptosis, in ABCB1- and ABCG2-overexpressing human cancer cell lines." (PMID 31905792, 2019). "Efflux transporters (e.g., P-gp/ABCB1, ABCC1, and ABCG2) and influx transporters (e.g., SLC22A16) are involved in Dox resistance in cancer cells." (PMID 31293428, 2019). "In the present study, we revealed an additional action of TMP195 on resensitizing ABCB1- and ABCG2-overexpressing multidrug-resistant cancer cells to multiple therapeutic drug substrates of ABCB1 and ABCG2." (PMID 31905792, 2019). "So far, 49 members of human ABC transporter family have been discovered; among them, P-glycoprotein (P-gp, also referred to ABCB1 or MDR1) and ABCG2 (MXR or BCRP) which are the important members of ABC family attribute to MDR in cancer cells." (PMID 31814840, 2019). "Overexpression of P-glycoprotein (Pgp, ATP-binding cassette subfamily B member 1 (ABCB1), multidrug resistance protein 1 (MDR1)), an ATP-binding cassette (ABC) transporter, plays a critical role in the MDR profile pumping anticancer drugs out of cancer cells." (PMID 31137684, 2019). "Overexpression of ATP-binding cassette (ABC) transporters, such as ABCB1 and ABCG2, has been proved to be a major trigger for multidrug resistance (MDR) in certain types of cancer." (PMID 31472682, 2019). "Therefore, whether ABCB1 knockout mice are cancer-prone in the wild remains to be investigated." (PMID 31249297, 2019). "The expression of ATP-binding cassette (ABC) transporters such as ABCB1 (also known as MDR1 or P-glycoprotein/P-gp), which efflux a range of anticancer drugs, is an important drug resistance mechanism in cancer cells." (PMID 31728254, 2019). "The first member of the ABCB family, ABCB1, also known as P-glycoprotein (P-gp), is the most extensively studied ABC transporter to induce MDR in cancer cells." (PMID 30641875, 2019). "It is worth mentioning that verapamil, a known inhibitor (and also a transport substrate) of ABCB1, was more effective in reversing ABCB1-mediated resistance to paclitaxel and vincristine in KB-V-1 and NCI-ADR-RES cancer cells." (PMID 31905792, 2019).
cancer (continued). "We confirmed that TMP195 reversed ABCB1- and ABCG2-mediated drug resistance by enhancing drug-induced apoptosis in ABCB1- and ABCG2-overexpressing multidrug-resistant cancer cells." (PMID 31905792, 2019). "The most known ABC transporters are ABCB1 and ABCC1, involved in the multidrug resistance phenotype in cancer, given their participation in cellular detoxification." (PMID 29491856, 2018). "Herein, we show that TS265 is a promising chemotherapeutic agent against cancer cells refractory to DOX therapy, capable of bypassing the efflux pump (ABCB1) overexpression responsible for resistance against DOX." (PMID 30061701, 2018). "A “multitarget multiribozyme” (MTMR) containing three trans-acting hammerhead ribozymes that, after autocatalytic self-activation, cleave the transcripts of the ABC transporter genes ABCB1, ABCC2, and ABCG2 tested positive in several cancer cell models." (PMID 29401721, 2018). "ATP binding cassette (ABC) transporters such as P-glycoprotein (ABCB1), MDR-1 and ABCG2 (BCRP, breast cancer resistance protein) lead to drug efflux and multidrug resistance, which is a major problem in cancer treatment." (PMID 29757250, 2018). "So there was no significant change in the IC50 values of cisplatin in the human cancer cell lines (KB-C2, NCI-H460/MX20, and KB-CV60) or transfected cell lines (HEK293/ABCB1, HEK293/G2, and HEK293/MRP1) compared with the corresponding parental cells." (PMID 30356705, 2018). "Studies have shown that ABCB1 and ABCG2 are overexpressed in many multidrug resistant cancer cells including ovarian, colon, lung, breast, and melanoma cancers." (PMID 30544754, 2018). "Multidrug resistance (MDR) triggered by ATP binding cassette (ABC) transporter such as ABCB1, ABCC1, ABCG2 limited successful cancer chemotherapy." (PMID 29455646, 2018). "Our current study includes assessment of select ABC superfamily gene members (including ABCB1, ABCC1, ABCC2 and ABCG1) known to act as active drug transporters to reduce accumulation of chemotherapy drugs within resistant cancer cells." (PMID 30477242, 2018). "The cytotoxicity assay indicated that the IC50 values of olmutinib for ABCB1-, ABCG2-, and ABCC1-overexpressing cancer cells (KB-C2, NCI-H460/MX20 and KB-CV60) were 11.42, 12.19, and 17.14 μM." (PMID 30356705, 2018). "Overexpression of ABC drug transporters (ABCB1/MDR-1/P-gp) mediates resistance toward taxanes and vinca alkaloids, and is a common feature of human cancer including NSCLC." (PMID 30087852, 2018). "ATP- binding cassette sub-family B member 1 (ABCB1), also known as P-glycoprotein 1 and multidrug resistance protein 1 (MDR1), is responsible for the efflux of anthracyclines and taxanes in cancer cells." (PMID 29180117, 2018). "Among these transporters, the ABC transporter subfamily B member 1 (ABCB1) and the ABC transporter subfamily G member 2 (ABCG2) are known to play an important role in mediating multidrug resistance in cancer cells." (PMID 30544754, 2018). "We have chosen three ABC-transporters, i.e., P-glycoprotein (MDR1/ABCB1) and breast cancer resistance protein (BCRP/ABCG2) as well-known MDR-mechanisms and ABCB5 as novel efflux transporter relevant for cancer stem-like cells." (PMID 29707146, 2018). "The effects of LS-2-3j on enhancing the sensitivity of ABCB1- and ABCG2-overexpressing cells to conventional anti-cancer drugs were further detected by the intracellular DOX- and MITX-associated mean fluorescence intensity (MFI) using flow cytometry." (PMID 30544754, 2018). "ATP-binding cassette transporters (ABCG2 and ABCB1) and multidrug-resistant protein 1 (MDR1) are important multi-drug resistant genes, which are also considered stem-like cell markers for many cancers." (PMID 28881812, 2017). "Three ATP-binding cassette (ABC) drug transporters, ABCB1 (p-glycoprotein/MDR1), ABCC1 (MRP1), and ABCG2 (BCRP), have been reported to be critical determinants in the cancer drug resistance." (PMID 28903328, 2017).
cancer (continued). "Among these members, the three efflux transporters ABCB1 (P-glycoprotein), ABCC1 (the multidrug resistance protein 1 (MRP1)), and ABCG2 are recognized as major contributors to multidrug resistance in human cancer cells." (PMID 28880238, 2017). "Consistent with this notion is our data showing that EGFR was activated by MUC1 in PTX-resistant cancer cells and more importantly, MUC1 inhibition resulted in diminished activity of EGFR and reduced expression of ABCB1 leading to reversal of PTX resistance." (PMID 28796259, 2017). "We also studied whether ABCB1 (P-glycoprotein) and ABCG2 (BCRP, breast cancer resistance protein), which are usually considered the main drug transporters underlying the multidrug resistance (MDR) phenotype in cancer cells, compromise the antiproliferative effects of EF-24 in K562 cells." (PMID 29088066, 2017). "Gambogic acid is reported to enhance the cytotoxicity of two clinically popular anti-cancer drugs, docetaxel and adriamycin in MCF-7/Adm cells via inhibition of ABCB1 through its protein degradation by proteasome pathway." (PMID 28587082, 2017). "Overexpression of the human multidrug resistance gene, ABCB1, was also recently reported to reduce GSK461364 activity in cancer cells." (PMID 28036269, 2017). "Resistance to this drug is mainly related to the MDR phenotype of cancer cells and to the level of MDR1 (ABCB1) expression." (PMID 28611294, 2017). "Similar to ABCB1, ABCB5 increases the efflux of drug molecules from cancer cells and, by doing so, promotes their chemo-resistance." (PMID 28677036, 2017). "ABC proteins responsible for multidrug resistance in human cancers include the multidrug resistance protein 1 (MRP1/ABCC1), P-glycoprotein (P-gp/ABCB1), and the breast cancer resistance protein (BCRP/ABCG2)." (PMID 28409029, 2017). "Upregulated genes included members of the tumor necrosis factor superfamily (TNFRSF9, TNFRSF11B, and TNFSF8), ABC transporters (ABCB1 and ABCG2), and nuclear factor (NF)-κB-related genes (NFKB2 and RELB), all of which induce stemness in cancer cells." (PMID 28423353, 2017). "The availability of ABCB1 and ABCG2 selective inhibitors should help surmount the selectivity hindrance to the application of JC1 on the isolation of cancer cells over expressing one or the other transporter and somatic stem cells overexpressing ABCG2." (PMID 28380010, 2017). "ABCB1 was the first ABC protein to be identified and cloned, as it was highly expressed in the tumours of cancer patients." (PMID 28409029, 2017). "The second MDR assay with specific MDR inhibitors showed that verapamil and MK-571 increased intracellular dye concentrations, confirming the involvement of the ABCB1 and ABCC1 in the eATP-induced efflux activity in two cancer cell lines." (PMID 29152126, 2017). "Multi-drug resistant protein (MRP) and P-glycoprotein (P-gp, ABCB1) are known mediators for drug resistance in cancer cells." (PMID 28076324, 2017). "In previous reports, CD44 expression has been linked to chemoresistance based on ABC transporter overexpression including ABCB1 and ABCC2 in various tumors especially in the cancer stem cell compartment." (PMID 29371972, 2017). "The data on the methylation patterns of ABCB1, ABCC1 and ABCG2 provided in the present study will help in selecting appropriate cancer cell lines for investigating the mode of action and/or testing the efficacy of (epigenetic) anticancer drugs." (PMID 27689338, 2016). "The present study demonstrates that TUBB3 transcription can be controlled by FOXO3a-mediated ABCB1 regulation and can subsequently promote the profusion of multiple cross-resistance and govern the tumor progression of PTX-resistant cancers." (PMID 27284014, 2016). "To overcome the chemoresistance ability in cancer cells and/or CSCs, we designed a TALEN-based oncolytic viral vector approach as a genome editing tool to knockout the ABCB1 gene and inhibit over expression of P-gp in CSCs." (PMID 27454254, 2016).
cancer (continued). "Knowledge of the promoter methylation patterns of ABCB1, ABCC1 and ABCG2 in cancer cell lines will be helpful, e.g. in selecting an appropriate cell line for investigating the mode of action and/or testing the efficacy of potential chemotherapeutic drugs." (PMID 27689338, 2016). "The clinical relevance of the major ABC-transporters ABCB1, ABCC1, and ABCG2 for failure of chemotherapy and poor survival prognosis of cancer patients has been shown." (PMID 27092478, 2016). "Along with the overexpression of P-gp (ABCB1), progress in determining other key molecular events that lead to the onset of multiple cross-resistance in PTX-resistant cancers has been greatly hampered." (PMID 27284014, 2016). "The expression of CD133, ABCB1, Bcl-2, and ALDH1A1 in the fused cells explains the increased drug resistance of the fused cell, suggesting that the cancer cell would acquire drug resistance through cell fusion with the stem cell." (PMID 26846780, 2016). "This review will focus on sub-family B, member 1 (ABCB1) as well as sub-family C, member 10 (ABCC10) and their influence on paclitaxel’s performance in cancer cells." (PMID 26633515, 2015). "ABCB1, BRCA1, GSTP1, and IGF2 displayed both an increased CM fraction and hyper-methylation in cancer." (PMID 26659027, 2015). "Overexpressing the adenine triphosphate (ATP)-binding cassette (ABC) transporters, particularly ABCB1 (MDR1/P-glycoprotein), ABCC1 (MRP1) and ABCG2 (BCRP), are one of most common reasons to result in MDR in cancer cells." (PMID 25915534, 2015). "The ATP-binding cassette (ABC) multidrug transporters such as ABCB1 (MDR1/P-glycoprotein), ABCC1 (MRP1) and ABCG2 (BCRP/MXR) are considered to be accountable for the majority of drug efflux in human cancers." (PMID 26515463, 2015). "Although ABCB1, C1 and G2 are the three usual suspects in multi-drug resistance, other ABC transporters also play roles in drug metabolism and beyond in cancer biology." (PMID 26517919, 2015). "To date, sixteen members have been identified, but only three major ABC drug transporters, including ABCB1 (P-glycoprotein), ABCC1 (multidrug resistance protein 1, MRP1) and ABCG2 (BCRP), are thought to affect cancer chemosensitivity." (PMID 26431273, 2015). "P-glycoprotein (P-gp), also known as ATP-binding cassette sub-family B member 1 (ABCB1), is an ATP-dependent drug efflux pump for xenobiotic compounds which often leads to multi-drug resistance to anti-cancer drugs." (PMID 26540166, 2015). "Previously, we showed that lapatinib inhibited the function of ABC transporters (including ABCB1, ABCC1 and ABCG2) and enhanced the anticancer activity of chemotherapeutic agents in ABC transporter-overexpressing cancer cells." (PMID 26036634, 2015). "Other than ABCB1, ABCG2 is a high-capacity transporter widely expressed in drug resistant cancer cells." (PMID 26431273, 2015). "MCF-7/ADR-1024 and MCF-7/ADR express high levels of drug transporter ABCB1 gene, detoxifying gene GST-π, basal-like gene N-cadherin and cancer stem cell surface marker CD44 gene." (PMID 25635866, 2015). "These cancer stem cells express a number of ABC transporters including ABCG2, ABCB1, ABCB5, and ABCC1." (PMID 26649310, 2015). "The overexpression of ATP-binding cassette (ABC) transporters, particularly ABCB1, ABCC1 and ABCG2, play a key role in mediating MDR by pumping anticancer drugs out from cancer cells." (PMID 26556876, 2015). "P-glycoprotein (P-gp; multidrug resistance protein 1, MDR1; ABCB1) is a plasma membrane efflux pump with broad ligand specificity in normal cells and in cancer cells." (PMID 25866761, 2015). "The P glycoprotein (P-gp, ABCB1) can limit the anticancer activity, via the efflux of drugs in particular in chemo-resistant cancer cells." (PMID 25706633, 2015). "The predominate means by which cancer cells resist Paclitaxel exposure is via up-regulation of the transmembrane transport protein ATP binding cassette B1 (ABCB1), also known as P-glycoprotein 1 (P-gp)." (PMID 26029917, 2015).